FLT3 (fms related receptor tyrosine kinase 3)
Diseases named in the same sentence as FLT3 in open-access papers (continued):
Sharing a sentence is not in itself a finding about the gene and the disease.
acute myeloid leukemia (continued). "The second-generation FLT3 inhibitor gilteritinib was approved for the treatment of adult patients who have relapsed or refractory acute myeloid leukemia (AML) with an FLT3 mutation, as detected by an FDA-approved test." (PMID 36831175, 2023). "FLT3 mutation is commonly present in newly diagnosed patients with acute myeloid leukemia, and confers high relapse risk." (PMID 37190240, 2023). "According to one clinical study, patients with FLT3-ITD mutated acute myeloid leukemia who relapsed less than 6 months after initial treatment have a dismal prognosis with median overall survival of fewer than four months." (PMID 37715270, 2023). "The most frequent mutation that involves FLT3, which can occur in up to 30% of acute myeloid leukemia (AML) cases, is the internal tandem duplication (ITD) of its juxtamembrane domain." (PMID 37391442, 2023). "Over 30–35% of patients suffering from acute myeloid leukemia express mutations of FLT3-ITD and FLT3-TKD, consequently resulting in the prolonged activation of proteins that promote cell proliferation and survival." (PMID 37374055, 2023). "Acute myeloid leukemia (AML) patients bearing the ITD mutation in the tyrosine kinase receptor FLT3 (FLT3-ITD) present a poor prognosis and a high risk of relapse." (PMID 37653435, 2023). "Activating fms-like tyrosine kinase 3 (FLT3) mutations in patients with acute myelogenous leukemia (AML) are common and associated with aggressive disease and poor survival." (PMID 36526260, 2023). "Internal tandem duplication mutations in the FLT3 tyrosine kinase receptor (FLT3-ITD) are associated with poor prognosis in patients with acute myeloid leukemia." (PMID 37190162, 2023). "In patients with cytogenetically normal acute myeloid leukemia, in whom FLT3‐ITD is a common mutation, overexpression of genes from the BER, NER, Fanconi anemia (FA), MMR, and HR pathways was associated with poor clinical prognosis." (PMID 36131612, 2023). "Mutations in Tet2 and Flt3-ITD (Fms Related Receptor Tyrosine Kinase 3—internal tandem duplication) in mice result in fully penetrant lethal acute myeloid leukaemia followed by extensive remodeling of DNA methylation." (PMID 36982935, 2023). "Internal tandem duplication (ITD) of the FMS-like tyrosine kinase (FLT3) gene is associated with poor clinical outcomes in patients with acute myeloid leukemia." (PMID 36823555, 2023). "Acute myeloid leukemia (AML) patients have frequent mutations in FMS-like receptor tyrosine kinase 3 (FLT3-mut AML), who respond poorly to salvage chemotherapies and targeted therapies such as tyrosine kinase inhibitors (TKIs)." (PMID 38023123, 2023). "SBI-0206965 induces caspase-dependent apoptosis in FLT3-ITD-mutated acute myeloid leukemia (AML) cells by inhibiting autophagy and increasing the reactive oxygen species levels." (PMID 36674464, 2023). "Isolated FLT3-ITD mutation cannot be responsible for the occurrence of acute myeloblastic leukemia, and it must be associated with other molecular abnormalities: NPM1 mutation, AML1-ETO gene fusion, NUP98 fusion, CBFβ-SMMHC fusion gene, and TET 2 deletion." (PMID 37892567, 2023). "Midostaurin is present in all three stages of the currently suggested frontline treatment regimen for FLT3-mutated acute myeloid leukemia submitted in the 2022 ELN recommendations." (PMID 37958832, 2023). "Activating mutations of FMS-like tyrosine kinase 3 (FLT3) are among the most frequently detected genetic alterations in acute myeloid leukemia (AML), accounting for approximately 30–35% of all patients." (PMID 36691065, 2023). "The FMS-like tyrosine kinase 3 (FLT3) gene mutated in 10–15% of pediatric acute myeloid leukemia (AML) is associated with an inferior outcome." (PMID 37760526, 2023). "Here, we reposition FLT3, one of the most frequently mutated drivers of acute myeloid leukemia (AML), as a prognostic marker and therapeutic target of BP-CML." (PMID 37932786, 2023).
acute myeloid leukemia (continued). "Olweus and colleagues identify a T cell receptor reactive against the recurrent D835Y driver mutation in FLT3 in acute myeloid leukemia and show that engineered T cells against this neoantigen provide efficient immunotherapy." (PMID 37783807, 2023). "The staurosporine analog midostaurin, marketed as RydaptTM and TauitmoTM, is approved for the treatment of newly diagnosed acute myeloid leukemia cases that have mutations in the FMS-like tyrosine kinase 3 (FLT-3) tyrosine kinase." (PMID 38132962, 2023). "Histone deacetylation inhibitors (e.g., LBH589) increase UBCH8 levels, favoring the degradation of a mutated form of fms related receptor tyrosine kinase 3 (FLT3) associated with acute myeloid leukemia." (PMID 37711589, 2023). "Gilteritinib has been approved as monotherapy in adults with acute myeloid leukemia (AML) FLT3 mutated with relapsed or refractory disease, in light of its advantages in terms of survival and the favorable safety profile." (PMID 37239765, 2023). "In recent years, many large sample studies have reported the important pathological role played by the activation of FLT3 mutation in the occurrence and progression of acute myelocytic leukemia(AML)." (PMID 35571096, 2022). "Much effort has been put into understanding Flt3 signaling in hematopoietic development as mutations that render the receptor constitutively active are frequent in acute myeloid leukemia (AML) and confer a poor clinical outcome." (PMID 35806293, 2022). "FLT3-ITD mutations are common druggable alterations in patients with acute myeloid leukemia (AML) and associated with poor prognosis." (PMID 35387132, 2022). "As expected, P22077, HBX19818, and its analogs inhibited the growth of acute myeloid leukemia harboring an FLT3 mutation." (PMID 35627217, 2022). "FLT3-internal tandem duplication (ITD) mutation analysis in DNA samples is essential for optimal clinical management in patients with acute myeloid leukemia (AML)." (PMID 36010999, 2022). "FLT3 mutations are the most frequently identified gene aberrations found in acute myeloid leukemia (AML) and indicate adverse clinical outcomes." (PMID 36159964, 2022). "Acute myeloid leukemia (AML) with mutations in the FMS-like tyrosine kinase (FLT3) is a clinically unresolved problem." (PMID 34665271, 2022). "Gilteritinib received approval for the treatment of FLT3-mutated relapsed or refractory acute myeloid leukemia in Japan in 2018." (PMID 35523692, 2022). "FLT3 mutations are one of the most common genetic alterations in acute myeloid leukemia (AML) and are identified in approximately one-third of newly diagnosed patients." (PMID 36185253, 2022). "FLT3 mutations are the most common genomic alteration detected in acute myeloid leukemia (AML) with a worse clinical prognosis." (PMID 36293564, 2022). "Acute myeloid leukemia (AML) harboring an activating mutation in FLT3 represents around one third of AML cases and is characterized by high relapse rate and dismal prognosis despite undergoing allogeneic hematopoietic cell transplantation (allo-HCT)." (PMID 35460465, 2022). "In a recent paper, Braun and coworkers investigated the preclinical effects of the LIMK1/2 inhibitor CEL_Amide in FLT3-ITD mutated Acute Myeloid Leukemia cells." (PMID 35805176, 2022). "FLT3 is the most common mutation site in acute myeloid leukemia, and the mutation of FLT3 increased the expression level of RIPK1 and the sensitivities of necroptosis." (PMID 35864548, 2022). "In older/unfit newly diagnosed patients with FLT3 mutated acute myeloid leukemia (AML), lower intensity chemotherapy (LIC) in combination with either a FLT3 inhibitor or with venetoclax results in poor overall survival (median 8 to 12.5 months)." (PMID 35501304, 2022).
acute myeloid leukemia (continued). "The fms-like tyrosine kinase 3 (FLT3) inhibitor gilteritinib is indicated for relapsed or refractory (R/R) FLT3-mutated acute myeloid leukemia (AML), based on its observed superior response and survival outcomes compared with salvage chemotherapy (SC)." (PMID 35637252, 2022). "Genetically heterogeneous disorder acute myeloid leukemia (AML) is marked by recurring mutations in FLT3." (PMID 35267471, 2022). "Internal tandem duplication (ITD) in FLT3 is the most frequent mutation found in acute myeloid leukemia (AML) with normal karyotype." (PMID 35053612, 2022). "FLT3 internal tandem duplication (FLT3-ITD) mutations occur in approximately 25% of adult acute myeloid leukemia (AML) patients and usually confer an adverse prognosis." (PMID 36050712, 2022). "Gilteritinib is the first and only FDA-approved fms-like tyrosine kinase 3 (FLT3) inhibitor for the treatment of adults with relapsed or refractory acute myeloid leukemia (R/R AML) with a FLT3 mutation as a monotherapy." (PMID 36296409, 2022). "Internal tandem duplications (ITD) of the FMS-like tyrosine kinase 3 (FLT3) predict poor prognosis in acute myeloid leukemia (AML) and often co-exist with inactivating DNMT3A mutations." (PMID 34903841, 2022). "In acute myeloid leukemia (AML) internal tandem duplications of the FLT3 gene (FLT3-ITD) are associated with poor prognosis." (PMID 34316017, 2022). "Approximately 30% of acute myeloid leukemias (AML) carry poor prognosis FLT3 mutations, most commonly internal tandem duplications (ITD) that constitutively activate kinase activity and aberrant signaling via STAT5 to promote proliferation and survival." (PMID 35681619, 2022). "Midostaurin (PKC412) is currently used for the treatment of patients with acute myeloid leukemia harboring FLT3-mutation." (PMID 36230769, 2022). "Gilteritinib is an orally available FDA-approved drug used for the treatment of patients with acute myeloid leukaemia (AML) harboring FMS-like tyrosine kinase 3 (FLT3) mutation." (PMID 35814226, 2022). "Disease relapse is a common cause of treatment failure in FMS-like tyrosine kinase 3 (FLT3) mutated acute myeloid leukemia (AML)." (PMID 35625776, 2022). "FLT3 is one of the most commonly mutated genes in acute myeloid leukemia, accounting for 15%-35% of newly diagnosed patients." (PMID 36185253, 2022). "Further, FLT3 mutations were found in one-third of newly diagnosed acute myeloid leukemia patients, and FLT3 internal tandem duplication was associated with relapse and inferior survival." (PMID 34417556, 2022). "FLT3–ITD mutations are present in approximately 20% of acute myeloid leukemia (AML) cases, and they are associated with leukocytosis, an increased risk of relapse, and a shorter overall survival (OS)." (PMID 36497281, 2022). "A 53-year-old female patient with acute myeloid leukemia (FLT3-ITD) at high risk received RIC-PBSCT." (PMID 34190149, 2021). "FLT3 mutations are the most frequently identified genetic alterations in acute myeloid leukemia (AML) and are associated with poor prognosis." (PMID 34217323, 2021). "The patient (female, 53 years old, Han nationality) was diagnosed with acute myeloid leukemia (FLT3-ITD) at high risk." (PMID 34190149, 2021). "FMS-like tyrosine kinase-3 (FLT3) is a receptor tyrosine kinase commonly mutated in acute myeloid leukemia (AML)." (PMID 33592069, 2021). "Approximately 30% of patients with newly diagnosed acute myeloid leukemia (AML) harbor mutations in the fms-like tyrosine kinase 3 (FLT3) gene." (PMID 34045454, 2021). "Via inhibitor library screening, we found that gilteritinib, a TKI approved for treating relapsed or refractory FLT3-positive acute myeloid leukemia (AML), can overcome these resistance mutations." (PMID 33627640, 2021). "An anti-FMS-related tyrosine kinase 3 (FLT-3) mAb with Ser239Asp and Ile332Glu mutations is part of a clinical phase I/II trial to treat patients with acute myeloid leukemia (AML) (ClinicalTrials.gov identifier: NCT02789254)." (PMID 33467027, 2021).
acute myeloid leukemia (continued). "Acute myeloid leukemia (AML) frequently has activating mutations in the FMS-like tyrosine kinase-3 gene (FLT3), which are a poor prognostic marker." (PMID 34203994, 2021). "A recently characterized example is mediated by the FMS-like tyrosine kinase 3-internal tandem duplication (FLT3-ITD) mutation in acute myeloid leukemia (AML), where the FLT3-ITD upregulates miR-155 expression via intron retention in its host gene." (PMID 34572454, 2021). "FLT3 internal tandem duplication (FLT3-ITD) is a frequent mutation in acute myeloid leukemia (AML) and remains a strong prognostic factor due to high rate of disease recurrence." (PMID 34876631, 2021). "Vandetanib, cabozantinib, and sorafenib have inhibitory activity against FLT3 kinase along with growth inhibitory activity against acute myeloid leukemia cells with FLT3 mutation." (PMID 33419162, 2021). "Acute myeloid leukaemia patients positive for the FLT3-ITD mutation (August 2020, Bloemfontein, Free State, South Africa)." (PMID 34230878, 2021). "Internal tandem duplications (ITD) mutation within FMS-like tyrosine kinase 3 (FLT3), the most frequent mutation happens in almost 20% acute myeloid leukemia (AML) patients, always predicts a poor prognosis." (PMID 34820336, 2021). "In patients with FLT3‐mutated relapsed/refractory acute myeloid leukemia, the FLT3 inhibitor gilteritinib induced deep molecular responses characterized by FLT3–internal tandem duplication (FLT3‐ITD) mutation clearance." (PMID 33340276, 2021). "Activating mutations of the fms-like tyrosine kinase 3 gene (FLT3) by internal tandem duplications (ITDs) in the juxtamembrane domain (JMD) have been reported in ~30% of adult acute myeloid leukemia (AML) patients with cytogenetically normal karyotype (CN)." (PMID 34711001, 2021). "Xospata is indicated as monotherapy for the treatment of adult patients who have relapsed or refractory acute myeloid leukaemia (AML) with a FLT3 mutation (see sections 4.2 and 5.1)." (PMID 34790681, 2021). "Examples of such “precision medicine” include the BCR-ABL fusion gene in chronic myeloid leukemia (CML), PML-RARA fusions in acute promyelocytic leukemia (APL) and FLT3 mutations in acute myeloid leukemia (AML)." (PMID 34425749, 2021). "FLT3 mutation is present in 25–30% of all acute myeloid leukemias (AML), and it is associated with adverse outcome." (PMID 33592069, 2021). "Using a hybridization capture-based chemistry and optimized bioinformatics pipeline, we show that next generation sequencing can reliably detect FLT3-internal tandem duplication and classify its allelic ratio for acute myeloid leukemia risk stratification." (PMID 31471587, 2020). "Here, embryonic morphogen FST is identified as a novel biomarker and therapeutic target for human FLT3/ITD‐mutated acute myeloid leukemia." (PMID 32134197, 2020). "Acute myeloid leukaemia (AML) carrying internal tandem duplication (ITD) of Fms-Like Tyrosine kinase 3 (FLT3) gene is associated with high risk of relapse and poor clinical outcome upon treatment with conventional chemotherapy." (PMID 32102366, 2020). "For example, SBI‐0206965 was reported to be cytotoxic to glioblastoma, neuroblastoma and lung cancer cells, and MRT68921 potentiates chemosensitivity in mesothelioma and induces apoptosis and autophagy in FLT3‐ITD‐mutated acute myeloid leukemia." (PMID 33040463, 2020). "Acute myeloid leukemia (AML) with fetal liver tyrosine kinase 3 (FLT3) internal tandem duplication (ITD) is associated with poor prognosis, and allogeneic stem cell transplantation (Allo-SCT) seems to be the preferred therapeutic approach." (PMID 32333156, 2020). "The mutations of NPM1 and FLT3-ITD represent the most frequent genetic aberration in acute myeloid leukemia." (PMID 33374216, 2020). "The US Food and Drug Administration recently approved FLT3 inhibitors midostaurin and gilteritinib in FLT3 mutation-positive acute myeloid leukemia." (PMID 31471587, 2020).
acute myeloid leukemia (continued). "Midostaurin, in combination with chemotherapy, was the only drug approved by the FDA for the treatment of adult patients with newly diagnosed FLT3 mutation-positive acute myeloid leukemia (AML)." (PMID 32595510, 2020). "Internal tandem duplication of Fms‐like tyrosine kinase 3 (FLT3/ITD) occurs in about 30% of acute myeloid leukemia (AML) and is associated with poor response to conventional treatment and adverse outcome." (PMID 32134197, 2020). "In Acute Myeloid Leukemia, mutations on the FLT3 tyrosine kinase receptor, such as FLT3-ITD are associated with a poor outcome in patients." (PMID 32151059, 2020). "FLT3 is another significant candidate, with mutations in this gene being common in acute myeloid leukaemia." (PMID 32872585, 2020). "FLT3-internal tandem duplication is associated with adverse prognosis in acute myeloid leukemia, particularly in patients with normal or intermediate risk karyotype." (PMID 31471587, 2020). "Up to now, ULK1 as a potential target for autophagy activity regulation has been reported in a large amount of the literature, and ULK1 inhibitors have been reported to function in lung cancer cells, FLT3‐ITD‐mutated acute myeloid leukemia and neuroblastoma." (PMID 33040463, 2020). "We recently identified the CDC25A phosphatase as a key actor in proliferation and differentiation in acute myeloid leukemia expressing the FLT3-ITD mutation." (PMID 32024878, 2020). "The US Food and Drug Administration recently approved type I inhibitors midostaurin and gilteritinib for treatment of adult acute myeloid leukemia patients harboring an FLT3 mutation." (PMID 31471587, 2020). "Oncogenic mutations in the FLT3 gene resulting in constitutively active FLT3 variants are frequently found in acute myeloid leukaemia (AML) patients and correlate with patient’s poor survival." (PMID 33003568, 2020). "Activating FMS-like tyrosine kinase 3 (FLT3) mutations are detected in about one-third of patients with acute myeloid leukemia (AML) at diagnosis." (PMID 33212779, 2020). "The cell-of-origin of NPM1- and FLT3-mutated acute myeloid leukemia (AML) is still a matter of debate." (PMID 31936647, 2020). "FLT3-ITD mutations in newly diagnosed acute myeloid leukemia (AML) are associated with worse overall survival (OS)." (PMID 32366841, 2020). "Multiple tyrosine kinase inhibitors (TKIs) have demonstrated clinical activity in FLT3-mutated acute myeloid leukemia (AML), including midostaurin, sorafenib, gilteritinib, quizartinib, and crenolanib." (PMID 33032648, 2020). "The internal tandem duplication (ITD) mutations of FMS-like tyrosine kinase 3 (FLT3) occur in approximately 25% of acute myeloid leukemia (AML) cases and are associated with poor therapeutic efficacy and short survival." (PMID 32284743, 2020). "The prognosis of acute myeloid leukemia (AML) with FMS-like tyrosine kinase 3 internal tandem duplication (FLT3-ITD) mutations is poor." (PMID 32284743, 2020). "FLT3/ITD is one of the most commonly mutated genes in acute myeloid leukemia, an aggressive hematological malignancy with poor prognosis." (PMID 32134197, 2020). "An activating mutation of Fms-like tyrosine kinase 3 (FLT3) is the most frequent genetic alteration associated with poor prognosis in acute myeloid leukemia (AML)." (PMID 32848159, 2020). "Constitutive activation of FLT3 by internal tandem duplications (ITD) in the juxtamembrane domain has been causally linked to acute myeloid leukaemia." (PMID 32155324, 2020). "Approximately 30% of patients with acute myeloid leukemia (AML) have an internal tandem duplication (ITD) or tyrosine kinase domain (TKD)-activating mutation in the fms-like tyrosine kinase 3 gene (FLT3)." (PMID 32545904, 2020). "Activating mutations in FMS-like tyrosine kinase 3 (FLT3) are present in up to 35% of patients with acute myeloid leukemia (AML)." (PMID 31819100, 2019).